CXCL12 (C-X-C motif chemokine ligand 12)
Diseases named in the same sentence as CXCL12 in open-access papers (continued):
Sharing a sentence is not in itself a finding about the gene and the disease.
cancer (continued). "Many of the molecules driving homing and retention of leukemic cells in tissues have been identified; among them, the CXCL12/CXCR4 axis has been shown to be essential for hematopoietic stem cell (HSC) migration and homing and also for cancer cell migration and metastasis." (PMID 32432042, 2020). "Besides LIF and TGFβ, there are some key regulatory molecules such as CXCL12 and SLIT2 in the model which are cancer progression and prevention players, respectively." (PMID 32384110, 2020). "Standard therapy may present some detrimental aspects such as tissue damage, hypoxia and cancer cell apoptosis through the release of proinflammatory cytokines such as TNF-alpha, granulocyte-colony stimulating factor (G-CSF), CXCL12, CCL2-4 and ICAM1." (PMID 32708431, 2020). "The niche-derived molecules regulating cancer cell dormancy include a chemokine stromal cell-derived factor 1 [SDF-1, also known as C-X-C motif chemokine ligand 12 (CXCL12)] that binds to its receptor C-X-C chemokine receptor type 4 (CXCR4) on cancer cells and anchors the cancer cells in the niche." (PMID 32232008, 2020). "In this context, DPP-4 could cleave/inactivate CXCL12 and downregulate the CXCL12/CXCR4 axis, subsequently inhibiting cancer cell growth, invasiveness and metastasis." (PMID 31991851, 2020). "According to the major role of CXCL12 axis in TME, lots of antagonists targeting CXCL12axis were proposed as monotherapy to promote antitumor immunity or in combination with other immunotherapies for cancer treatment." (PMID 33363463, 2020). "CXCL12 is an important target in cancer metastasis and up until now, there has been no FDA approved drug available in the market for its inhibition." (PMID 33092204, 2020). "In TNBCs, stromal CAFs were identified as the source of IGF-1 and CXCL12, which were shown to prime cells to home the CXCL12- and the IGF1-rich bone microenvironment, in a process dependent on CXCR4 and IGF-1R expression by cancer cells." (PMID 33364239, 2020). "The CXCL12/CXCR4 (C-X-C motif chemokine 12/C-X-C motif chemokine receptor 4) axis plays a crucial role in tumorigenesis, metastasis, and chemoresistance, and therefore is an ideal target for cancer immunotherapy." (PMID 32917034, 2020). "In addition, the CXCL12/CXCR4/CXCR7 and CCL20/CCR6 chemokine axes are known to promote migration and the invasiveness of cancer." (PMID 32775427, 2020). "Chemokine CXCL12 and its receptor CXCR4 are constitutively overexpressed in human cancers." (PMID 31802362, 2020). "Furthermore, many studies have determined that CXCL12/CXCR4 axis potentiates proliferation, angiogenesis, invasion and migration of various cancers, including glioma, colorectal carcinoma, renal cancer, pancreatic cancer and ovarian cancer." (PMID 33129326, 2020). "For instance, CXCL12-elicited bone pain induced by cancer while siRNA or inhibitor of CXCR4, a CXCL12 receptor, could antagonize CXCL12-elicited pain in spinal neurons." (PMID 32434423, 2020). "ACKR3 generally is not considered a chemotactic receptor, however, addition of CXCL12 enhances ACKR3+/CXCR4+ cancer cell migration across endothelial cells toward CCL19 and CXCL13, chemokines expressed by endothelial cells inside the lymph nodes." (PMID 30800123, 2019). "A number of antagonists and inhibitors targeting the CXCL12/CXCR4/ACKR3 axis are being developed in cancer indications, mostly in non-brain tumor related cancers and not in combination with radiotherapy." (PMID 30813533, 2019). "Of these genes, CXCL12, a chemokine and its cell surface receptor, CXCR4, and CXCR2 which are known to be involved in cancer cell proliferation and metastasis were verified by qRT-PCR to be significantly increased by ~3-fold in the HCC97L cells transfected with the CPE-ΔN expression plasmids." (PMID 31798768, 2019).
cancer (continued). "The results reported herein indicate that inhibition of PI3K phosphorylation may be a major mechanism by which CXCL12 antibody and LY294002 inhibits cancer cell proliferation and invasion and induces apoptosis." (PMID 31500630, 2019). "We found that radiation induced the up-regulation of the chemokine CXCL12 and its receptor CXCR4, of the metalloproteinases 9 and 12 (MMP9 and MMP12), and of key transcription factors involved in the expression of genes related to migration of cancer cells." (PMID 30813636, 2019). "CXCL12 is a CXC homeostatic chemokine, constitutively expressed by blood and stromal cells, which retains a central role in the regulation of embryogenesis, hematopoietic system, tissue repair mechanisms and cancer biology." (PMID 29989007, 2018). "We recently reported the capacity of triple negative cell lines to induce a cancer stem cell (CSC)-like phenotype and invasion properties into luminal cells, a mechanism mediated by pro-inflammatory cytokines that up-regulated the CXCL12/CXCR4/CXCR7 chemokine signaling axis." (PMID 29928478, 2018). "The wound healing assay shows that the delivered CXCR4 siRNA significantly suppresses the wound closure, suggesting that silencing CXCR4 effectively inhibits cell migration, which is consistent with the findings that CXCL12/CXCR4 signaling enhances the migration and invasion of cancer cells." (PMID 30242189, 2018). "On the other hand, it was shown that both CXCR4 and CXCR7 responded to CXCL12 to greatly increase human lymphoma cells’ migration, indicating that CXCR7 might be an efficient target for cancer treatment." (PMID 29977203, 2018). "Nonetheless, the data do not suggest that CXCL12 was unavailable for activating CXCR4 on the cancer cells." (PMID 29088715, 2017). "The developmental role for CXCL12 and CXCL14 chemokines in CT differentiation is fully consistent with their recognised functions in adult fibrosis processes, such as in chronic fibrotic pathologies and cancer-induced fibrosis." (PMID 29222527, 2017). "The activation of CXCL12/CXCR4 axis enhances migration and invasion of cancer cells, thus leading to metastasis and may regulate antitumor immune response through T cells access." (PMID 28774348, 2017). "Our group has found that CXCR4+ cancer cell migration in 2D is CXCL12 isoform-specific, but isoforms have not been examined and compared in 3D settings." (PMID 29117251, 2017). "The microarray data detected expression of CXCL12 mRNA in the ACC samples, and CXCL12 may have been made by cancer cells below the limit of detection by IHC." (PMID 29088715, 2017). "To investigate whether activation of CXCL12/CXCR4 axis promotes EMT, we performed the assays of RT-PCR and Western blot to determine the expressions of E-cadherin and vimentin in cancer cells." (PMID 28176874, 2017). "The expression of CXCL12, the unique CXCR4 ligand, significantly increased in the collective invasion area where p16INK4A-immunopositive senescent cells were present, whereas CXCR4 was diffusely overexpressed in all cases of cancer tissues." (PMID 28489070, 2017). "Thus, molecular markers of CAFs, such as fibroblast activation protein (FAP), C-X-C motif chemokine ligand 12 (CXCL12), and hepatocyte growth factor (HGF) are emerging as selective therapeutic targets in the cancer stroma." (PMID 28346486, 2017). "It is likely that some of the miRNAs might involve in the activation of CXCL12/CXCR4 axis and therefore play an important role in cancer progression and metastasis." (PMID 28176874, 2017). "Furthermore, in various cancer models metastasis of cancer cells was revealed to be mediated by CXCR4 activation and directed migration towards CXCL12 expressing organs." (PMID 26920352, 2016). "Among them, CXC ligand 12 (CXCL12, also called stromal-derived factor-1), one of CXC chemokines, was previously shown to have important impacts on proliferation and invasion of many types of cancer cells, via its specific receptor, CXCR4." (PMID 27542220, 2016).
cancer (continued). "Notably, CXCL12/CXCR4 appears to be important for site-specific metastasis of several cancers; CXCR4-positive cancer cells invade along CXCL12 gradients thus promoting metastasis to CXCL12-expressing organs such as lymph nodes, lung, livers and bone." (PMID 27213454, 2016). "Therefore, the CXCL12/CXCR4 axis contributes to the establishment of an appropriate microenvironment in the bone, or a “pre-metastatic niche”, for osteotropic cancers like breast, and prostate." (PMID 27618899, 2016). "Our previous study demonstrated that ACC-derived CAFs might promote cancer invasion by expressing MMP2 and CXCL12 in vivo, but it remained unclear how CAFs promote ACC cell invasion." (PMID 26954362, 2016). "In subsequent studies, immune suppression by the FAP α+ CAFs was mediated by CXCL12, the chemokine that binds to cancer cells and excludes T cells by a mechanism that depends on signaling by the CXCL12 receptor, CXCR4." (PMID 26985769, 2016). "Cancer cells often secrete MΦ2-type cytokines such as IL-10, CCL2, CXCL12, and VEGF." (PMID 27231721, 2016). "The secretion of C–X–C motif chemokine 12 (CXCL12), also known as stromal-derived factor 1 (SDF-1), by stromal cells in the bone marrow is known to attract osteotropic cancer cells via stimulation of the C–X–C chemokine receptor type 4 (CXCR4) receptor that is up regulated by many tumors." (PMID 27618899, 2016). "Among several chemokines, CCL1, −2, −4, −5, −7, −8, −12, −13, and IL6 might influence the interaction of inflammation with cancer malignancy, and CCL2, −3, −5, −7, CXCL12, −14, and IL6 were found to be able to affect the macrophage infiltration." (PMID 26790618, 2016). "Therefore, most of its anti-cancer activity is possibly mediated by direct binding to CXCR4 and interference with the interaction to its ligand (CXCL12)." (PMID 26646452, 2016). "We suggest that increased concentrations of CXCL12 and low levels of its specific receptor in EC might be results of improved ability of CXCR4 receptors to bind the higher amount of CXCL12 in cancer patients." (PMID 27041792, 2016). "Furthermore, in malignant mesothelioma (again the prototype model of interaction of cancer cell with normal mesothelial cells), SDF-1α/CXCL12 was proved to be involved in recruitment of mesothelioma stem-like progenitor cells." (PMID 25598217, 2015). "Evidence also suggests that p110γ can be directly involved in cancer cell migration and invasion, as it has been shown in MDA-MB-231 and in melanoma cells in response to the chemokine CXCL12." (PMID 25360116, 2014). "Among the chemokines, CXCL12, also known as stromal cell derived factor-1 (SDF-1), and its cognate receptor CXCR4 have been involved in cancer metastasis of several cancers where the CXCL12-CXCR4 axis is known to modulate phenomena such as chemotaxis, migration, proliferation, and angiogenesis." (PMID 25580125, 2014). "Since CXCR4 and CXCR7 are both involved in cancer malignancy, and in particular in GBM angiogenesis, molecules able to interact and block either CXCL12 itself or both receptors simultaneously could represent an improved pharmacological approach." (PMID 24904289, 2014). "Preclinical cancer models have revealed that directed metastasis of cancer cells is mediated by CXCR4 activation and migration of cancer cells is towards CXCL12 expressing organs while targeting CXCR4 impairs the spread of cancer cells and development of metastasis." (PMID 25471741, 2014). "CXCL12/CXCR4 signaling has been shown to activate a number of downstream signaling molecules, which are involved in the regulation of growth, aggressive phenotypes and therapy resistance in cancer cells." (PMID 25359780, 2014). "The interplay between CXCL12/CXCR4-CXCR7 and GABA/GABAA-GABAB receptors systems could have many physiological implications in neurotransmission, cancer and inflammation." (PMID 24808825, 2014).
cancer (continued). "Chemokine CXCL12 (stromal cell derived factor 1α or SDF-1α) is a key player in angiogenesis and impacts such diverse processes as inflammation, wound healing, embryonic development, and the growth of malignant tumors." (PMID 25084358, 2014). "The invasive behavior of cancer cells might indirectly depend on locally released CXCL2 that, via an autocrine mechanism, binds to CXCR4 impairing chemotaxis towards CXCL12-producing target organs and metastatic spread." (PMID 25484899, 2014). "CXCL12 interacts with the CXCR4 receptor to initiate several downstream effectors and intracellular signalling pathways that promote migration, invasion, adhesion and proliferation of various cancer cells (3, 16, 23 and 24)." (PMID 25237365, 2014). "CXCL12 signaling regulates chemotaxis and homing of stem cells to sites of injury, while perturbations of CXCL12 signaling through CXCR4 and/or CXCR7 drive pathogenesis of diseases such as cancer." (PMID 24896823, 2014). "Because TOV-21G cells highly express CXCL12/CXCR4 and CXCL16/CXCR6 axes in spite of a low response to EGF or TNF, these axes may contribute to cancer progression as described by others." (PMID 23800251, 2013). "Coupling of stromal cell derived factor 1 (SDF-1; CXCL12) with its receptor CXCR4, which was previously identified as a major coreceptor for the entry of T-tropic HIV, plays critical roles in inflammation, as well as cancer metastasis." (PMID 22485156, 2012). "This was confirmed in the cancer cell line MDA-MB-435 previously shown to express low endogenous levels of CXCR4, which also showed the CXCR4-CXCR7 double overexpressors to have the most chemotaxis to CXCL12." (PMID 22152016, 2011). "CXCR4/CXCL12 axis plays role in cancer cell metastasis and proliferation; the importance of the CXC4/CXCL12 axis may differ in different types of cancer cells, due to their discrete expression." (PMID 22074556, 2011). "CXCR4 together with its cognate ligand CXCL12 (stromal cell-derived factor-1/SDF-1) is widely expressed in various different cancers, and it is somewhat surprising that its expression did not correlate with patient survival." (PMID 22084725, 2011). "We also show that the level of CXCL12 expression in cancer cells is not a valuable prognostic factor in patients with advanced EOC." (PMID 21410972, 2011). "Events triggered by CXCL12 may play a part, as CXCL12 drives the migration of both CXCR4-positive cancer cells and macrophages and may promote a molecular crosstalk between them." (PMID 20946648, 2010). "CXCL12-driven stimulation of cancer cells and macrophages may elicit and reinforce a GM-CSF/HB-EGF paracrine loop, whereby macrophages contribute to cancer survival and expansion." (PMID 20946648, 2010). "The ability of miR-866-3p to decrease CXCL12 expression was also observed in primary stromal cells derived from long term marrow cultures and in non-stromal cancer cell lines known to express CXCL12." (PMID 21179442, 2010). "If HB-EGF released by mononuclear phagocytes can trigger the production of GM-CSF in cancer cells, a possible GM-CSF/HB-EGF paracrine loop may exist that is initially activated by CXCL12." (PMID 20946648, 2010). "Thus, CXCL12 induced the release of functional HB-EGF from mononuclear phagocytes, transactivation of HER1 and proliferation of cancer cells (HeLa and DLD-1), fibroblasts (Balb/c 3T3 cells) and endothelial cells (HUVEC)." (PMID 20946648, 2010). "Although these proteins have been previously linked to cancer cell survival, they have not been previously associated with CLL nor has PDCD4 been established as a downstream phosphorylation target of CXCL12 signaling." (PMID 20661426, 2010). "Cancer cells stained positive for CXCR4, CXCL12, HER1, HER4 and GM-CSF." (PMID 20946648, 2010). "RT-PCR and immunoblot analyses of HT29 cells revealed Bak expression was markedly increased in adherent and non-adherent carcinoma cells expressing CXCL12 relative to the transfection control GFP cells." (PMID 20877573, 2010).
cancer (continued). "Because inhibiting CXCR4 or CXCR7 only on 231-control cancer cells did not affect adhesion, these data further emphasize that basal treatment with CXCL12 acts through endothelial CXCR4 to significantly enhance adhesion of circulating cancer cells." (PMID 19484126, 2009). "Notably, cancerous tissues exhibited reduced CXCL12 levels compared with non-malignant tissues across cancers." (PMID 40166682, 2025). "CCL18, CCL22, CCL23, and CXCL12 consistently showed a negative correlation across most cancer types, while other anti-inflammatory chemokine genes displayed a more complex, context-dependent relationship, with both positive and negative correlations depending on the specific malignancy." (PMID 40806276, 2025). "Consequently, the observed reduction in CXCL12 and CCL22 levels in the presence of cancer cell spheroids may be partially due to the binding of these chemokines to their corresponding receptors." (PMID 40547518, 2025). "In CXCL12 synovial fibroblast cells from RA patients, SDC2 was found to have a role in extracellular matrix remodeling, suggesting that IRF1 may have a similar role in cancer." (PMID 40862725, 2025). "This phenomenon is attributed to MSCs, pre-adipocytes, and adipose tissue producing and secreting the chemokine CXCL12, which not only facilitates the homing of cancer cells but also, through its receptors CXCR4 and CXCR7, influences gene expression and proliferation in various cancers." (PMID 39518143, 2024). "Surprisingly, despite a clear activation of the non-canonical NF-κB pathway in the cancer cells tested, they did not secrete the chemokines CXCL12, CXCL13, CCL19 and CCL21, known to be induced as a consequence of activation of this signaling pathway upon LTβR stimulation of other cell types." (PMID 39215104, 2024). "Thus, the reduction in CXCL12 and CCL22 in the presence of cancer cell spheroids may be partially explained by the binding of these chemokines to their receptors." (PMID 37445941, 2023). "Interestingly, in our cohort, high TICs expression of CXCL12 rather than cancer-related CXCL12 expression predicts a good response to chemotherapy (p = 0.005)." (PMID 37966614, 2023). "On the other hand, the changes between M0 and S + M0 were detected for chemokines CXCL12 (from 0.09 to 0.06 ng/mL, p = 0.0102), CXCL16 (from 0.58 to 0.45 ng/mL, p = 0.0012), and CCL22 (from 0.37 to 0.11 ng/mL, p = 0.0037), demonstrating the inhibitory effect of the cancer cell spheroids." (PMID 37445941, 2023). "further found that cancer cells could restrict T-cell motility and suppress the intratumoral accumulation of T cells by assembling a transglutaminase-2 (TGM2)-dependent filamentous coating of CXCL12-keratin-19 (KRT19) heterodimers." (PMID 37359565, 2023). "CXCL12 exerts its function by binding to the seven-transmembrane G-protein-coupled receptor CXCR4 and CXCR7, which were expressed on a great diversity of cell types, including lymphocytes, hematopoietic stem cells, endothelial cells, epithelial cells, stromal fibroblasts, and cancer cells." (PMID 35079936, 2022). "Interestingly, CAF-S1 silenced for CXCL12 partly lost their ability to initiate EMT in cancer cells, while CXCL12-silencing had no impact in CAF-S4." (PMID 31964880, 2020). "Along these same lines, CXCL12 that was present in SASP of senescent papillary thyroid carcinoma (PTC) cells played key roles in inducing collective invasion of the cancer cells and in increasing the survival of non-senescent PTC cells, in a CXCR4-dependent manner." (PMID 32582148, 2020). "However, the chemokines and their receptors that particularly stimulate tumorigenesis, including CCR7, CXCL1, CXCL8, and CXCL12/CXCR4, could, consequently, act as poor prognostic markers for cancer patients." (PMID 31991604, 2020).